MIR1825 (microRNA 1825)
Synonyms: hsa-mir-1825; MIRN1825
Gene: MicroRNA gene on chromosome 20 (32,237,795 to 32,237,847, forward strand). Ensembl gene ENSG00000284125.
Homologues: Orthologues: chimpanzee ptr-mir-1825 (100% identical).